NPY (neuropeptide Y)
Diseases named in the same sentence as NPY in open-access papers (continued):
Sharing a sentence is not in itself a finding about the gene and the disease.
Obesity (continued). "Our study, however, did not confirm changes in the concentration of neuropeptide Y under the influence of traction forces, neither in the normal-weight group, nor in the group of women with obesity." (PMID 36927409, 2023). "Supplementation with decaffeinated green coffee extract in breast cancer survivors with obesity did not affect serum NPY levels." (PMID 37373115, 2023). "Deletion of LepR gene specifically in AgRP/NPY, but not in POMC/CART, neurons in the adult mice (to avoid compensatory effects of gene deletion) causes obesity under a standard chow diet." (PMID 37547309, 2023). "In light of such limitations, we did not further analyze other physiological obesity markers such as orexigenic peptides such as neuropeptide Y, ghrelin, CCK, or orexin in the present study." (PMID 36612600, 2022). "Particularly, after the development of hyperprolactinemia-induced obesity in these mice, a significant increase in mRNA levels of the orexigenic hormones agouti-related peptide (AGRP) and neuropeptide Y (NPY) were observed in the hypothalamic arcuate and dorsomedial nuclei, respectively." (PMID 36237192, 2022). "Besides a direct impact on adipose tissue, SCFAs can cross the blood–brain barrier and modulate neural circuits by releasing neuropeptide Y (NPY) that drives BAT activation and upregulation of thermogenesis in mouse models of obesity." (PMID 36031866, 2022). "The increased level of ROS and NO in the first-order neurons into arcuate nucleus, and the aberrant functioning of orexigenic Agouti-related protein (AgRP)/Neuropeptide Y (NPY), anorexigenic pro-opiomelanocortin (POMC)/cocaine- and amphetamine-regulated transcript (CART) can lead to obesity." (PMID 36501129, 2022). "Accordingly, NPFF2R deficient mice show exacerbated high-fat diet-induced obesity, despite lower caloric intake, due to lack of adaptive BAT thermogenesis and impaired hypothalamic neuropeptide Y signalling." (PMID 35105898, 2022). "Neuropeptide Y (NPY) is highly abundant in the brain and involved in various physiological processes related to food intake and anxiety, as well as human diseases such as obesity and cancer." (PMID 35165283, 2022). "Moreover, oxytocin (OXT), Neuropeptide-Y (NPY), and cortisol supported an almost direct propagation of stress to PTSD and obesity with different net effects." (PMID 35959009, 2022). "Hypothalamic inflammation affects both NPY and POMC and promotes obesity." (PMID 34307371, 2021). "Knockdown of NPY expression in the DMH promoted development of brown adipocytes through the sympathetic nervous system, increased energy expenditure, reduced food intake, and thus prevented diet-induced obesity." (PMID 34307371, 2021). "The human neuropeptide Y (NPY) Y2 receptor (Y2R) plays essential roles in food intake, bone formation and mood regulation, and has been considered an important drug target for obesity and anxiety." (PMID 33531491, 2021). "In summary, this study provides a link between obesity, NAFLD, and NPY." (PMID 34829968, 2021). "In those cases, ghrelin resistance was not limited to NPY/AgRP neurons, because ghrelin did not stimulate GH secretion in mice with diet-induced obesity." (PMID 34445772, 2021). "When obese-obesity prone rats were food-restricted to reduce body weight, NPY levels increased and remained high, indicating that NPY levels in these rats are not subject to metabolic regulation, but operate under a genetic set point." (PMID 34199898, 2021). "On one hand, the activation of TLR4 signal in AgRP/NPY and POMC neurons decreased the expression of AgRP/NPY and increased the expression of POMC, which induced the reduction of appetite and suggested to be involved in obesity." (PMID 34899611, 2021). "According to previous studies, the possible molecular mechanisms of its anti-obesity effects may involve the phosphatidylinositol 3-kinase (PI3K)/Akt signaling pathway and neuropeptide Y in the central nervous system." (PMID 32821266, 2020).
Obesity (continued). "Firstly, DMH NPY gene silencing improves overeating and obesity induced by a high-fat diet; in turn, DMH NPY overexpression leads to increased food intake and weight gain, aggravating diet-induced eating disorders and obesity." (PMID 33123166, 2020). "We also found a possible mechanism of CAP’s anti-obesity effect by enhancing PYY and GLP-1excretion in intestinal epithelial cells, which suppress NPY- and AgRP-expressing neurons and activate POMC- and CART-expressing neurons in the ARC of the hypothalamus, resulting in lower food intake." (PMID 32180694, 2020). "Although several studies have reported the contributions of NPY to obesity and T2DM, none of them have assessed the specific effects of NPY serum levels on obesity in distinct metabolic conditions." (PMID 32831640, 2020). "Finally, OJe modulated some obesity-related genes, such as leptin A, ghrelin, orexin, pro-opiomelanocortin (POMC), and neuropeptide Y (NPY), in both gut and brain." (PMID 31619003, 2019). "In addition to promoting energy consumption, signal molecules such as Leptin, Neuropeptide Y, and Nesfatin-1 could regulate the feeding center and the peripheral satiety system through calcium signaling to decrease food intake and reduce the energy acquisition, thereby decreasing obesity." (PMID 31195699, 2019). "Moreover, NPY-immunopositive neurons are activated in the DMH during fasting and in the obesity state." (PMID 30618603, 2018). "In addition, other top key connections such as NPY and GCG are also related to both obesity and Type 2 diabetes in humans." (PMID 29156709, 2017). "Mice lacking ROCK1 in either POMC or NPY/AgRP neurons, display impaired leptin sensitivity and obesity." (PMID 28270795, 2017). "Moreover, knockdown of NPY in the DMH ameliorates the hyperphagia, obesity and impaired glucose tolerance of OLETF rats, whereas viral-mediated overexpression of NPY in the DMH of intact rats causes hyperphagia and obesity." (PMID 28575002, 2017). "Interestingly, we found additional RSVs in patients in 4 of the selected genes (NPY, GRPR, SLCO4C1 and GRIK1) reinforcing their putative role in the pathophysiology of obesity." (PMID 28489853, 2017). "Knockdown of NPY in the DMH in normal weight Sprague-Dawley rats has been demonstrated to reduce the size of fat depots and ameliorate high-fat diet-induced hyperphagia and obesity." (PMID 27512691, 2016). "Overall, these studies examining factors that might modulate DMH NPY demonstrated a novel anorectic action of central TTR in the control of energy balance, providing a potential novel target for obesity treatment." (PMID 27512691, 2016). "Furthermore, DMH NPY knockdown increases iBAT thermogenesis and results in browning of WAT in subcutaneous inguinal fat in Sprague-Dawley rats and prevents diet-induced obesity." (PMID 26379628, 2015). "A HFD and chronic overexpression of NPY in the hypothalamic PVN of rats increased the ratio of total adipose tissue weight to body weight, which is consistent with the Lee index, the indicator of obesity." (PMID 25993471, 2015). "This suggested that NPY was produced by a non-neuronal component of the SVF that is induced with obesity." (PMID 23472120, 2013). "Moreover, sustained viral overexpression of NPY on hypothalamic nuclei such as the PVN, LH and DMH, results in increased food intake and body weight gain compared to controls, with rats developing obesity." (PMID 21799827, 2011). "Alarin-mediated pleiotropic NPY release from hypothalamic explants directly enters into the adipose tissue by activating NPY-Y2 receptors to influence GLUT4 mRNA expression in adipocytes of subjects as well as to accelerate glucose intake that stimulates appetite and obesity." (PMID 36246892, 2022).
Obesity (continued). "It is well known that hypothalamic inflammation reduces the responsiveness of POMC and NPY neurons in the ARC to the physiological actions of leptin and insulin and alters the normal activity of the orexigenic and anorexigenic peptides, thereby promoting energy imbalance and obesity." (PMID 35683029, 2022). "Specific NPY overexpression in central amygdala NPY neurons project to the Arc and PVN-NPY neurons, resulting in increased food intake and decreased energy expenditure, and thus the development of obesity, which can be attenuated by ablation of the NPY in the central amygdala." (PMID 34307371, 2021). "Similarly, NPY inhibition did not achieve clinically meaningful results to justify obesity treatment." (PMID 34680059, 2021). "The interaction between GAL and NPY in feeding and energy metabolism, the relationships between GAL and other substances involved in food intake mechanisms, the potential pharmacological strategies to treat food intake disorders and obesity and the possible clinical applications are discussed." (PMID 33802616, 2021). "The connection between NPY and leptin has been long recognized: on one hand, NPY is overexpressed in the hypothalamus of ob/ob mice, and its repetitive administration into the CNS was shown to suppress the SNS activity of BAT, decreasing energy expenditure and inducing obesity." (PMID 32069871, 2020). "Importantly, selective lack of NPY in CeA neurons attenuates the obesity phenotype, whereas excessive production of NPY in CeA further enhances that phenotype." (PMID 33123166, 2020). "Furthermore, research on differences in NPY levels between various obesity phenotypes has not been published." (PMID 32831640, 2020). "We hypothesized that maternal HF alters fetal neuroprogenitor cell (NPC) and hypothalamic arcuate nucleus (ARC) development with preferential differentiation of neurons towards orexigenic (NPY/AgRP) versus anorexigenic (POMC) neurons, leading to offspring hyperphagia and obesity." (PMID 33138074, 2020). "In conclusion, our findings suggest that macrophage derived NPY and its anti-inflammatory effects may serve to preserve normal adipose tissue function in the setting of obesity." (PMID 23472120, 2013). "However, whereas male and female germline Y1 receptor deficient mice exhibit reduced fasting-induced food intake, they exhibit slight or no reductions in total daily food intake or NPY-stimulated feeding, and they also develop late-onset obesity." (PMID 22768253, 2012). "The results of this study suggest that enhancing the catabolic effect of NPY-ergic Y2 receptors may open up potential new ways to treat obesity without any adverse effects on cortical bone mass, the major determinant of bone strength." (PMID 20613867, 2010). "Mice lacking NPY neurons develop obesity and hyperinsulinemia in response to a normal chow diet, but exhibit reduced weight gain and abnormal improvement in glucose tolerance under a high-fat diet, pointing to the role of NPY/AgRP neurons in coordinating nutrient distribution." (PMID 34307371, 2021). "Thus, it can be concluded that with normal NPY levels, peripheral Y2-receptor antagonist has no potential for treating obesity, but oppositely may even induce metabolic disorders." (PMID 29674968, 2018). "In this context, the identification of ARC neuromediators other than those released by the POMC/CART and NPY/AgRP/GABA neurons that could relay the catabolic message of leptin via the melanocortin system, appeared justified in our understanding of the pathophysiology of obesity." (PMID 28690493, 2017). "In a study of plasma NPY levels in adults with PWS, it was shown that NPY levels were within the lower normal range (despite obesity) and did not significantly change with GH treatment." (PMID 41516228, 2025). "This study is among the first to investigate DPP-4 and NPY peptides in human jejunal muscular tissue among patients with or without T2DM and obesity." (PMID 40142315, 2025).
Obesity (continued). "The authors suggested that elevated NPY levels in both obese and non-obese patients with PCOS indicate a role in the pathogenesis of the condition, independent of obesity." (PMID 40871560, 2025). "However, our study reveals that maternal obesity does not affect AgRP circuits during early postnatal life whereas it affects POMC axonal projections, suggesting that distinct mechanisms underlie the effects of maternal HFHS feeding on POMC neurons versus AgRP/NPY neurons." (PMID 32163401, 2020). "In contrast, ablation of mitofusins in NPY/AgRP neurons disrupts mitochondrial fusion without inducing ER stress and alleviates HFD-induced obesity." (PMID 28270795, 2017). "Biochemical profiles of hormones involved in obesity including T4, T3, insulin growth factor (IGF), leptin, AGRP, ghrelin, and NPY were all measured at baseline and after LHA-DBS with no change following stimulation." (PMID 26819774, 2016). "In addition, Guzelkas’ group conducted a cross-sectional study, reporting that serum NPY and leptin concentrations are higher in adolescent girls aged 14 to 18 years diagnosed with PCOS, with or without obesity." (PMID 40871560, 2025). "In a single-cell transcriptomics analysis of the hypothalamus, it has been shown that, in long-term diet-induced obesity, the expression of CREB is reduced in AgRP/NPY neurons; however, no previous study has evaluated the impact of the short-term consumption of an HFD on Pomc CREB." (PMID 35805082, 2022). "Additionally, leptin inhibits NPY and activates POMC, creating a negative feedback loop that prevents obesity." (PMID 32987812, 2020). "Importantly, neither the inhibition of NPY nor the inhibition of POMC in OP mice were capable of modifying their phenotype, which reinforces the hypothesis that an early reduction of POMC following the introduction of a HFD is involved in the increased predisposition to obesity." (PMID 27373214, 2016). "Indeed, it can be suggested that without the continuing inhibition of nicotine, NPY, and POMC gene expression can rebound to that equal to an early postnatal age, leading to hyperphagia and future obesity." (PMID 22848202, 2012). "In addition, NPY upregulation may influence VPA anticancer treatment of neuroblastomas, and counteracting hypothalamic NPY effects may help improve VPA-induced weight gain and obesity without interfering with the desired central effects of VPA." (PMID 37239168, 2023).
Anxiety (221 papers, 2004 to 2026). Intense feelings of nervousness, tension, or panic often arise in response to interpersonal stresses. "Collectively, available data highlight local NPY-mediated neuromodulation of the LC underlying the peptide’s anxiety-relieving properties, under both naïve and stressed conditions." (PMID 40749333, 2025). "Elevated NPY levels have also been associated with reduced anxiety- and depressive-like behaviors, while lower NPY levels often correlate with heightened stress sensitivity and more pronounced depressive-like symptoms." (PMID 40490517, 2025). "For instance, certain SNPs have been associated with a higher risk of anxiety following early-life stress, likely due to changes in NPY expression and reduced HPA axis regulation." (PMID 41300812, 2025). "Previous research has shown that neuropeptide Y, which is linked to anxiety levels, is associated with LOAUD." (PMID 40767639, 2025). "In the mirror test, the acute cold stress-treated NPY-deficient zebrafish displayed anxiety-like behaviors such as staying stationary and swimming along the side of the tank." (PMID 38732113, 2024). "In this experiment, the NPY gene in zebrafish was knocked down, and the NPY-deficient zebrafish displayed several anxiety-like behaviors, including decreased social interaction in the mirror test and decreased locomotion in the black–white test." (PMID 38732113, 2024). "Neuropeptide Y (NPY) is a 36 amino-acid peptide that has been implicated in the modulation of feeding behavior, fear, anxiety, seizures, pain perception, stress responses, and memory." (PMID 38585909, 2024). "Neuropeptide-Y (NPY) and dopamine are neurotransmitters associated with anxiety and stress-related psychiatry through receptors." (PMID 38487579, 2024). "Another NPY SNP is 1002T > G, associated with low NPY content in the CSF and amygdala, which is linked to higher levels of anxiety, arousal, addictive behaviours, and decreased stress resilience." (PMID 36982313, 2023). "NPY is an endogenous neuropeptide associated with stress, cardiovascular physiology, anxiety, depression, and diabetes." (PMID 34949748, 2022). "The current researches have consistently pointed out that NPY mainly counteracts alcoholism anxiety and stress-related symptoms caused by CRF in alcohol dependence, which suggests the effect of NPY on emotional homeostasis." (PMID 36245887, 2022). "On one hand, reduced NPY activity in cortical circuits has been associated with a plethora psychiatric disorders including anxiety, depression, and PTSD in both preclinical and clinical studies." (PMID 35800635, 2022). "The abnormal expression of NPY has been linked to a wide range of disorders, including epilepsy, anxiety and depression, and metabolic disorders." (PMID 36429060, 2022). "Neuropeptide Y (NPY) is a neurotransmitter that has been implicated in the development of anxiety and mood disorders." (PMID 34867217, 2021). "Additional studies also reported altered expression of NPY and PV in the context of epilepsy and behavioral changes associated with it, including anxiety, corroborating findings linking these neuromodulators with both pathologies." (PMID 34025410, 2021). "NPY not only directly stimulates vasoconstriction associated with platelet aggregation to promote thrombosis, but also induces anxiety, which contributes substantially to platelet activation by activating Y2R in the hypothalamus and striatum." (PMID 33708805, 2021). "After the emergence of spontaneous seizure, the expression of NPY and PV was evaluated on different limbic structures associated with both epileptogenesis and anxiety." (PMID 34025410, 2021). "Accumbal NPY has been implicated in alcohol intake, drug addiction, food intake, anxiety, and depression, as suggested by studies of alterations in NPY expression by intra-NAc injections of NPY or receptor agonists/antagonists." (PMID 34298907, 2021).